STH (saitohin)
Synonyms: MAPTIT
Tractability: No criterion of Open Targets' tractability assessment is met for any kind of drug.
Gene: Protein-coding gene on chromosome 17 (45,999,250 to 45,999,694, forward strand). Ensembl gene ENSG00000256762.
Subcellular location: Cytoplasm; Nucleus
Subcellular location (Human Protein Atlas): Golgi apparatus; Nucleoplasm; Cytosol
Gene Ontology:
Molecular function: protein binding
Biological process: positive regulation of mRNA splicing, via spliceosome
Cellular component: cytoplasm; cytosol; nucleoplasm; nucleus; perinuclear region of cytoplasm
Genetic constraint (gnomAD): Loss-of-function variants: 2 observed, 0.57 expected, observed/expected ratio (o/e) 3.52. That is too few expected variants to judge how well the gene tolerates losing a copy. Missense variants: 131 observed, 158.04 expected, observed/expected ratio (o/e) 0.83, 90% interval 0.72 to 0.96. Synonymous variants: 36 observed, 61.93 expected, observed/expected ratio (o/e) 0.58, 90% interval 0.44 to 0.77.
Diseases named in the same sentence as STH in open-access papers:
STH is named in the same sentence as 10 diseases in open-access papers, as found by Europe PMC text mining. Sharing a sentence is not in itself a finding about the gene and the disease. The quoted sentences say what the papers report.
frontotemporal dementia (3 papers, 2006 to 2023). Frontotemporal dementia (FTD) comprises a group of neurodegenerative disorders, characterized by progressive changes in behavior, executive dysfunction and language impairment, as a result of degeneration of the medial prefrontal and frontoinsular cortices. "The STH gene has also been associated with autosomal dominant frontotemporal dementia (FTD), progressive supranuclear palsy (PSP) and Pick's disease." (PMID 16603077, 2006).
COVID-19 (2 papers, 2022 to 2024). A disease caused by infection with severe acute respiratory syndrome coronavirus 2. "Among these overlapping genes, nonsynonymous SNPs in the exons across SPPL2C, CRHR1, MAPT, STH, and KANSL1 genes were identified, among which, 13 were from COVID-19 critical illness and 15 were from COVID-19 hospitalization." (PMID 39764106, 2024).
schizophrenia (2 papers, 2016 to 2023). A major psychotic disorder characterized by abnormalities in the perception or expression of reality. "The possible contribution of internal MAPT transcripts such as saitohin (STH) to MAPT regulation or function makes it of special interest in relation to tauopathies, other dementias and, more recently, schizophrenia." (PMID 27030133, 2016).
tauopathies (2 papers, 2016 to 2017). "The special localization of STH gene in a functionally critical position of the tau gene could explain its role in tauopathies." (PMID 28211174, 2017). "The fact that STH is known to bind MAPT makes it of direct interest in relation to MAPT interactions, and the observation that complete single exon ORF STH may exist only in hominoids is noteworthy because monkeys appear much less prone to tauopathies and clinical features of Alzheimer’s." (PMID 27030133, 2016).
adenoma (1 paper, 2022). A neoplasm arising from the epithelium. "Non-functioning adenomas were the most common adenoma type (N = 42, 71.2%), followed by STH-producing (n = 10, 16.9%) and ACTH-producing adenomas (N = 4, 6.8%)." (PMID 35049709, 2022).
degenerative diseases (2 papers, 2015 to 2023). "The STH gene is a polymorphic gene nested within an intron of the MAPT gene and encodes the protein Saitohin, which has been found to be susceptible to multiple degenerative diseases and neuropsychiatric disorders." (PMID 40729198, 2023).
STH also shares sentences with these, for which no sentence is quoted: Parkinson disease (2 papers); dementia (1); epilepsy (1); psychiatric disorder (1).